GGCX (gamma-glutamyl carboxylase)
Description:
Mediates the vitamin K-dependent carboxylation of glutamate residues to calcium-binding gamma-carboxyglutamate (Gla) residues with the concomitant epoxidation of vitamin K hydroquinone to vitamin K epoxide. Couples epoxidation and carboxylation in the same active site. Catalyzes gamma-carboxylation of blood coagulation factors (F2, F7, F9 and F10) and anticoagulants such as PROC, which are essential for thrombosis. Catalyzes gamma-carboxylation of osteocalcin/BGLAP, which is essential for bone metabolism. Catalyzes gamma-carboxylation of matrix Gla protein (MGP) and other transmembrane gamma-Gla proteins such as PRRG2, which are essential for calcium homeostasis and haemostasis.
Synonyms: VKGC; VKCFD1
Tractability: Small molecule: an approved drug acts on it; a structure with a bound ligand is known; it belongs to a druggable protein family. Antibody: UniProt predicts a signal peptide or a membrane-spanning region. PROTAC: ubiquitination databases record sites on it; its protein half-life has been measured.
Target class: Enzyme; Lyase
Gene: Protein-coding gene on chromosome 2 (85,544,720 to 85,561,819, reverse strand). Ensembl gene ENSG00000115486.
Subcellular location: Endoplasmic reticulum membrane
Pathways (Reactome):
Disease: Defective gamma-carboxylation of F9
Metabolism of proteins: Gamma-carboxylation of protein precursors
Gene Ontology:
Molecular function: gamma-glutamyl carboxylase activity; vitamin binding
Biological process: negative regulation of neurotransmitter secretion; vitamin K metabolic process; blood coagulation; peptidyl-glutamic acid carboxylation; protein modification process; negative regulation of bone development; negative regulation of testosterone biosynthetic process; protein maturation
Cellular component: endoplasmic reticulum membrane; membrane; endoplasmic reticulum lumen
Genetic constraint (gnomAD): Loss-of-function variants: 62 observed, 86.23 expected, observed/expected ratio (o/e) 0.72, 90% interval 0.58 to 0.89. The upper end of that interval is the gene's LOEUF score, 0.89, which puts it in group 3 of 6, group 1 being the genes least tolerant of losing a copy. Missense variants: 748 observed, 886.76 expected, observed/expected ratio (o/e) 0.84, 90% interval 0.79 to 0.9. Synonymous variants: 344 observed, 351.69 expected, observed/expected ratio (o/e) 0.98, 90% interval 0.89 to 1.07.
Gene-disease validity (ClinGen):
ClinGen rates the evidence that GGCX causes each of these diseases.
vitamin K-dependent clotting factors, combined deficiency of, type 1 (autosomal recessive): Definitive. Combined vitamin K-dependent clotting factors deficiency (VKCFD) is a congenital bleeding disorder resulting from variably decreased levels of coagulation factors II, VII, IX and X, as well as natural anticoagulants protein C, protein S and protein Z.
pulmonary arterial hypertension (autosomal dominant): Moderate. Pulmonary arterial hypertension (PAH) is a group of diseases characterized by mean pulmonary artery pressure >20 mmHg and elevated pulmonary arterial resistance leading to right heart failure.
Homologues: Orthologues: chimpanzee GGCX (99% identical), macaque GGCX (97% identical), rabbit GGCX (92% identical), mouse Ggcx (89% identical), rat Ggcx (89% identical), guinea pig GGCX (89% identical), dog GGCX (88% identical), pig GGCX (83% identical), tropical clawed frog ggcx (65% identical), zebrafish ggcx (38% identical), Drosophila melanogaster GC (36% identical).